STAT1 (signal transducer and activator of transcription 1)
Diseases named in the same sentence as STAT1 in open-access papers (continued):
Sharing a sentence is not in itself a finding about the gene and the disease.
tumor (continued). "Our study revealed that the TME endowed TAMs with high ID1 expression, which interacts with STAT1 to inhibit CCL4 and SerpinB2 transcription, two STAT1 target genes, leading to CD8+ T cell exclusion in tumor sites and cancer stemness traits maintenance." (PMID 37996458, 2023). "In summary, we leverage single-cell analyses to dissect the cellular dynamics in the tumor microenvironment (TME) following neoadjuvant chemotherapy and provide a pre-clinical rationale for modulating STAT1 in combination with anti-PD-1 for TNBC patients." (PMID 37055410, 2023). "Analysis of DEGs revealed an upregulation of STAT1, STAT4, and CXCL11, indicating the activation of anti-tumor and immunomodulatory pathways." (PMID 37842640, 2023). "Inhibition of cancer stem cell self‐renewal through reduced expression of STAT1 and CD44 in tumour tissues incubated with EV‐encapsulated napabucasin." (PMID 37294158, 2023). "Immunofluorescence analyses confirmed a striking increase in the nuclear localization of STAT1 (the activated form) and increased MHC-II expression in B7-H3 knockdown tumor cells when compared with control tumor cells." (PMID 36869048, 2023). "We further confirmed the direct interaction between STAT1 and ID1 in HEK 293T cells, RAW 264.7 cells, and CD68+ TAMs in CRC patient tumor tissues by using Co-IP, proximity ligation assay (PLA) and confocal imaging." (PMID 37996458, 2023). "This, in turn, activates the signal transducer and activator of transcription 1 (STAT1) and nuclear factor κB (NF-κB) pathways in the brain metastatic cells to promote tumor growth and chemoresistance." (PMID 37569410, 2023). "For this reason, we also detected the effect of compound 25 on STAT1 and STAT5 phosphorylation in tumor cells." (PMID 37240202, 2023). "Further research has revealed that GZMA interacts with the F2R receptor on the surface of tumor cells, activating the JAK2/STAT1 signaling pathway, inducing tumor cell apoptosis, and T cell-mediated tumor killing." (PMID 37884883, 2023). "On the whole, it was illustrated that higher the expression of STAT1, STAT2, STAT3, STAT4, STAT5A, and STAT5B, the lower the tumor purity." (PMID 36968603, 2023). "STAT1 and STAT4 mainly contribute to cytokine production and cell-specific activity, which results in the anti-tumor effects of immune cells (MHC-I and checkpoint inhibitor upregulation)." (PMID 38094755, 2023). "STAT1 and STAT3 are also being explored for their tumor immunity-specific functions due to the increasing importance of immunotherapy, which refers to treatments that use the body’s own immune system to combat diseases." (PMID 38022653, 2023). "IL-12 was found to act directly on tumor cells to activate NF-κB and enhance IFN-γ-mediated STAT1 phosphorylation." (PMID 37504299, 2023). "We made similar observations for Stat1 and other STAT1 target genes including Irf1, Cxcl10, and Cxcl11, which suggested that PARP14 was induced specifically in IFNγ-inflamed tumours but independently of α-PD-1." (PMID 37752135, 2023). "When we combined higher values of STAT1 and a value of STAT6 between 0.15 and 0.75 the macrophage will transit to a pro-tumor macrophage M2d." (PMID 37283734, 2023). "In contrast to STAT1, STAT3 is generally described to have tumor-promoting properties, as it regulates the expression of genes involved in cell proliferation, apoptosis, and metastasis." (PMID 37561163, 2023). "Tumor-derived cytokines such as IL-6 and IL-27 have promoted PD-L1+CD8+ T cells development through STAT1/STAT3 signaling." (PMID 37077914, 2023). "Expression of these pathways can be further amplified in a STAT1-dependent manner via co-depletion of FAK and STAT3, resulting in extensive infiltration of tumour-reactive CD8 T-cells and further restraint of tumour growth." (PMID 36977556, 2023). "The biological function of STAT1 and STAT3 differs in terms of cell growth and induction of an anti-tumor immune response." (PMID 37047709, 2023).
tumor (continued). "Compound 25 had little effect on p-JAK, p-STAT1, p-STAT5, or other signaling pathways, implying that compound 25 selectively reduced STAT3 activation in tumor cells." (PMID 37240202, 2023). "FEGCG can inhibit the expression of PD-L1 induced by interferon and reduce the expression of STAT-1, P-STAT-1, IRF and PD-L1 through transcription level, thus inhibiting the growth of tumor cells." (PMID 37277118, 2023). "STAT1 expression was highly correlated with the immune score and ESTIMATE score and negatively correlated with tumor purity." (PMID 36854755, 2023). "This long-lasting tumor immunity is likely mediated by an IL-10 signaling pathway specific for intratumoral CD8+ T cells, IL-10-induced STAT1 and STAT3 phosphorylation, and IFN-γ expression in intratumoral CD8+ T cells." (PMID 37629156, 2023). "In the tumor lysates, the direct effects by poly(I:C)/IFN were shown by the increases of STAT1 levels." (PMID 36726024, 2023). "According to the results of oncomine, the expression of STAT1 was increased and the expression of STAT3/5A/5B were decreased in tumor tissues compared with normal tissues." (PMID 36862902, 2023). "In general, it was displayed that higher expression of STAT1, STAT2, STAT3, STAT4, and STAT5A indicated a lower tumor purity." (PMID 36968603, 2023). "Selected genes are reflecting main anti-tumor immune pathways, such as Th1 signaling (IFNG, TBX21, CD8A/B, IL12B, STAT1 and IRF1), Th1 chemoattraction (CXCL9, CXCL10 and CCL5) and cytotoxic functions (GNLY, PRF1, GZMA, GZMB and GZMH)." (PMID 37726776, 2023). "For example, STAT1 can suppress the growth and invasion of tumors, whereas STAT3 inhibits apoptosis and induces tumor cell proliferation and tumor-promoting inflammation." (PMID 37047709, 2023). "However, abnormal low expression of STAT1 may create conditions for tumour immune escape." (PMID 36524848, 2023). "STAT1 then upregulates IRF1 to repress the expression of SLC7A11 and SLC3A2, the two subunits of the glutamate-cystine antiporter system xc-, to limit tumor cell cystine uptake, resulting in tumor cell lipid peroxidation and death." (PMID 36672246, 2023). "can induce cancer cell ferroptosis and effectively inhibit tumor cell growth by up-regulating MHC class I molecule of tumor cell and activating endogenous IFN- γ signal through STAT1 signaling pathway." (PMID 37007121, 2023). "Signal transducer and activator of transcription 1 (STAT1), the first member of the STAT family, is generally considered a tumor suppressor due to its ability to resist pathogen infection and its vital role in the immune response." (PMID 38188683, 2023). "IFN-λ acts in conjunction with related genes such as STAT1, STAT2, and STAT3 to affect the JAK-STAT signaling pathway, which promotes tumor progression." (PMID 37697300, 2023). "It is becoming increasingly clear that cell-intrinsic inflammatory signaling in cancer cells with CIN can have tumor-promoting as well as tumor-suppressive effects mediated by STAT3 (and NF-κB) and STAT1 signaling, respectively." (PMID 37561163, 2023). "This is also supported by the positive correlation of STAT1 and STAT3 expression in human HCC samples in tumor and immune cells, indicating high immunological tolerance in a subset of HCC patients, as evident by PD-L1 expression." (PMID 35267462, 2022). "The adequate balance between STAT1 and STAT3 expression is very crucial for driving the macrophage polarization and tumor progression." (PMID 34689394, 2022). "STAT1 and STAT3 protein expression were strongly and positively correlated in the tumor cells and infiltrating immune cells." (PMID 35267462, 2022). "PD-L1 TPS, indicating tumor-specific, and PD-L1 CPS, indicating immune cell and tumor-specific staining, both strongly correlated with STAT1 expression and with cytotoxic CD8- and FOXP3-positive cells." (PMID 35267462, 2022).
tumor (continued). "The findings of our study shed light on the role of STAT1 expression and regulation by HNSCC cells on tumour development and the immune response during HNSCC." (PMID 35595823, 2022). "The apoptotic and amplifying activities of this compound are related to the inhibition of JAK/STAT signaling, as it can prevent STAT1 phosphorylation by inhibiting JAK and STAT3, which reduces the activity of antiapoptotic genes and induces tumor cell death." (PMID 36193062, 2022). "But in tumor models, EZH2 inhibits the expression of pro-inflammatory genes and pathways, such as SOCS3, STAT1, STAT3, etc.." (PMID 35432300, 2022). "Tumor-derived type III collagen is necessary to sustain tumor dormancy, as its interference restores tumor cell proliferation through DDR1-mediated STAT1 signaling." (PMID 36430404, 2022). "To explore the mechanism by which APS promote the differentiation and immunosuppressive function of MDSC, we observed the effect of APS in the levels of p-STAT1 and p-STAT3 in MDSC which were sorted from tumor-bearing mice by flowcytometer." (PMID 36159871, 2022). "Consistent with the IHC results, human PCa tumor samples exhibited a significant enhancement in the expression of JAK1 and STAT1 compared to that observed in benign tissues." (PMID 36065066, 2022). "Patients that respond to PD-1 blockade also exhibited increased expression of STAT1, CXCL9, CXCL10, GZMB, CD8A, and CD8B, which is consistent with our observation in tumor model with IFNα-MSC treatment." (PMID 35145233, 2022). "Our results demonstrate that STAT1 and STAT3 are expressed and activated in HCC and tumor infiltrating immune cells." (PMID 35267462, 2022). "To further explore the role of STAT1 in tumor immunity, we used the GEPIA database to determine the correlation between STAT1 and the expression of immune cell biomarkers in HCC." (PMID 35646925, 2022). "Here we showed a redundant role of SPATA2 and CYLD in the regulation of STAT1 activation and IFN-γ-induced genes in tumor cells." (PMID 36531014, 2022). "It has been reported that IFN-γ-related gene expression contributes to immunotherapy prediction, such as CCR5, CXCL9, IFNG, STAT1, and PRF1, and these genes are related to tumor antigen presentation, T cytotoxic activity, and immune cell infiltration." (PMID 35432443, 2022). "In vivo studies showed that Siglec-15 RNAi inhibited tumor growth and increased the CD4+/CD8+ ratio; however, this was offset by the overexpression of STAT1 and STAT3." (PMID 35769818, 2022). "The secondary signals from tumor- and tumor stroma-derived factors including HMGB1, TLRs, TGFβ, and endoplasmic reticulum (ER) stress then pathologically activate MDSCs through STAT6, STAT1, and NF-κb signaling pathways." (PMID 36031601, 2022). "In our signature, the expression of STAT1 and FOXP3 is the main indicator of anti‐tumour response through sustaining T‐cell population which is tumour suppressive." (PMID 35043584, 2022). "In the tumor and its microenvironment, STAT1 and STAT3 have both been shown to be expressed by tumor cells and infiltrating immune cells and to be involved in regulating cancer adaptive immunity." (PMID 35267462, 2022). "By specifically deleting SPATA2 and CYLD in human and mouse CRC cell lines, we showed that these two proteins inhibit STAT1 accumulation and activation and subsequently CXCL10 expression in tumor cells." (PMID 36531014, 2022). "We observed similar correlations of the expression level of STAT1 and IFIT3 with activated dendritic cells, activated NK cells, CD8 T cells and memory activated CD4 T cells, which were representative cells for anti-tumor immunity estimated by the CIBERSORT." (PMID 36311733, 2022). "Constitutive phosphorylation of STAT1, STAT3, and STAT5 has been detected in many tumor cell models." (PMID 35401182, 2022). "Further experiments indicated that STAT1 and STAT3 contributed to tumor abrogation by Siglec-15 RNAi." (PMID 35769818, 2022).
tumor (continued). "In vivo experiments revealed that transfection with vectors expressing STAT1 and STAT3 inhibited the Siglec-15 RNAi-induced inhibition on tumor growth and the increases in CD4+/CD8+ ratio." (PMID 35769818, 2022). "Signal transducer and activator of transcription 3 (STAT3) is the main transcription factor mediating IL-6-induced signaling in tumor and immune cells, whereas interferon-γ (IFN-γ) signaling activates the closely related STAT1 protein." (PMID 35267462, 2022). "This interaction induced tumor suppression and T cell-mediated killing of tumor cells via the activation of the JAK2/STAT1 signaling pathway." (PMID 35256589, 2022). "In conclusion, we show that in the absence of STAT3, IL-6 induced prolonged STAT1 signaling and expression of STAT1 target genes, which suggests an interplay of STAT1 and STAT3 signaling in the presence of proinflammatory IL-6 in the tumor microenvironment." (PMID 35267462, 2022). "STAT1 was the crucial regulatory factor of PDL1-independent adaptive resistance, and knocking out STAT1 led better anti-tumor immune response." (PMID 35508972, 2022). "Type II interferon (IFN) and STAT1 signaling increase RGS1 expression and prevent T cell transport to tumor by inhibiting calcium influx and inactivating kinases ERK and AKT." (PMID 35879796, 2022). "In conclusion, our findings indicate that tumour-derived STAT1 regulates HNSCC tumorigenicity and PD-L1 immune checkpoint signalling, while T-cell-derived STAT1 is necessary for immune activation and anti-tumour immune responses." (PMID 35595823, 2022). "In esophageal squamous carcinoma, CLDN1 was revealed to promote tumor development and invasion via autophagy activation through the 5′AMP-activated protein kinase/STAT1/Unc-51 like autophagy activating kinase (ULK1) signaling pathway." (PMID 36193204, 2022). "Apigenin can also halt STAT3, STAT5 gene expression and enhance the activity of STAT1, STAT2 and LMWPTP, which inhibits cell proliferation, tumor invasion and tumorigenesis." (PMID 35807549, 2022). "Although the exact molecular mechanism has not yet been clarified, it was found that PTH-AS expression in T47D cells upregulates STAT1 and its downstream cancer-promoting IRDS and CCL5, resulting in enhanced tumor malignancies." (PMID 35618021, 2022). "Of note, the role of STAT-1 is unclear in cancer, because previous studies did show that, similar to TGF-β, STAT-1 had both an oncogenic and tumor-suppressing role." (PMID 36078078, 2022). "Generally, STAT1 and STAT3 are considered to have opposite effects, with STAT1 being considered a tumor suppressor and STAT3 an oncogene." (PMID 35806366, 2022). "Treatment of PDFS cells with RGFP966 and 5’-AZA also significantly increased the mRNA expression of other tumor suppressors, including EGR1, PTEN, STAT1, and immune stimulatory receptor CD40." (PMID 35646715, 2022). "We found markedly reduced SOCS1 levels accompanied by increased p-STAT1 and STAT1, decreased p-STAT3, and thus an increased p-STAT1/p-STAT3 ratio in miR-155–overexpressing EO771, 4T1, and AT-3 tumor cells compared with control cells." (PMID 35925680, 2022). "IFN-activated STAT1 promotes PDL1 expression in tumors, which further accelerates tumor progression." (PMID 36458816, 2022). "EGCG was identified as a potent inhibitor of STAT1 in IFN-γ elicited STAT1 activation in various cell lines suggesting the anti-inflammatory and anti-tumor action of EGCG." (PMID 36613784, 2022). "For example, lncRNA LINC00673 inhibits tumor progression via reinforcing the interaction of PTPN11 with PRPF19 and facilitated STAT1-dependent antitumor response." (PMID 34322379, 2021). "The JAK-STAT signaling pathway is a double-edged sword in CIT, and both STAT1 and STAT2 drive anti-tumor immune responses by inducing type I and type II interferon (IFN)." (PMID 34852825, 2021).
tumor (continued). "The STAT1 and STAT3 transcription factors have been identified as major players in tumor genesis and they are being considered promising targets for cancer therapy." (PMID 33846436, 2021). "All these markers except sIL-6Rα, OCLN, STAT1 and STAT3, are upregulated in tumor samples compared to controls." (PMID 33846436, 2021). "In IECs, expression of STAT1 gene was also predicted to be upregulated by inflammatory cytokines IL1β and IFNγ and growth factor FGF7 identified as key molecules involved in tumor microenvironment." (PMID 34946170, 2021). "Collectively, our findings suggest that the anti-tumor effects of DUSP26 are manifested through regulation of tumor cell proliferation/migration, apoptosis, and senescence via modulating YAP/ERK, Akt/AMPK and/or p38/STAT1 signaling pathways." (PMID 33718185, 2021). "Conventional T cells can differentiate into Tregs in response to IL-35-mediated STAT1/STAT3 signaling, yielding so-called iTr35 cells, which can mediate the relationship between IL-35 and tumor cells in TME, accelerating tumor cell growth and metastasis." (PMID 34093586, 2021). "Conversely, STAT1 knock-down (STAT1KD) in both wild-type and radioresistant nu61 HNSCC led to tumor growth suppression and radiosensitization." (PMID 34830176, 2021). "F-araA targets STAT1, a well-known component of the Janus kinase JAK/STAT signaling cascade acting as a tumor suppressor." (PMID 33300108, 2021). "EBV latency in tumor cells increases intracellular ROS activity and the MDR gene expression by activating the STAT1 signaling pathway and phosphorylated STAT1, promoting P-gp expression." (PMID 35087758, 2021). "Thus, STAT1 may exert tumor-suppressing or tumor-promoting effects to regulate tumor activity." (PMID 34943817, 2021). "Signal transducer and activator of transcription 1 (STAT1) signaling potentiates antitumor immune responses downstream of type I (IFNα/β) and II (IFNγ) interferons (IFNs), both within tumor cells and immune cells." (PMID 34083537, 2021). "We also observed increases in the frequency of CD11b+F480+ cells in the spleens of tumor-bearing WT mice, compared with STAT1-/- AOM/DSS animals in the early (day 20) and advanced stages of tumor development (day 77)." (PMID 34299314, 2021). "Yet, by downregulating STAT1, GSCs evade the inhibitory pressure of Type I IFNs in the TME and fuel tumor outgrowth." (PMID 34571733, 2021). "The network consists of a system of ordinary differential equations (ODEs) involving eight variables: concentrations of STAT1, STAT3, Bcl-2, BAX, IFN-β, JAK2 and DDP and tumour volume." (PMID 34631119, 2021). "STAT1 always plays opposite roles to STAT3 in tumorigenesis and mostly triggers antiproliferative and pro-apoptotic responses while enhancing anti-tumor immunity." (PMID 34746227, 2021). "Metabolic reprogramming of macrophages has been appreciated as an important factor for effective immune responses, including those that combat tumor growth, and our findings indicate that IFN/STAT1-induced NAMPT is a key component of this response." (PMID 33976173, 2021). "Such infiltration resulted from the induction of STAT1 and IRF7, and the expression and secretion of pro-inflammatory chemokines and cytokines (CCL5, CXCL10, and interferon-γ) in tumor cells in vitro and tumor plasma in vivo." (PMID 34681622, 2021). "In CRC context, some studies demonstrated that oncogenic KRAS is able to reduce the expression of IFNγ targeted genes in KRASMUT tumor cells (HCT-116 cells with KRASG13D), including STAT1 and MHC-II." (PMID 33691728, 2021). "STAT1, a protein involved in interferon (IFN) signal transduction, is known to mediate both tumor-suppressive and tumor-promoting pathways." (PMID 34943910, 2021). "Hyperactive IFN-γ/STAT1 signaling promotes M1-like TAM reprogramming, leading to vascular remodeling and consequent tumor eradication." (PMID 34692475, 2021).